EPCIP-AS1 (EPCIP antisense RNA 1)
Synonyms: C21orf49; C21orf62-AS1
Gene: Long non-coding RNA gene on chromosome 21 (32,772,100 to 33,019,751, forward strand). Ensembl gene ENSG00000205930.
Diseases named in the same sentence as EPCIP-AS1 in open-access papers:
EPCIP-AS1 is named in the same sentence as 1 disease in open-access papers, as found by Europe PMC text mining. Sharing a sentence is not in itself a finding about the gene and the disease.
EPCIP-AS1 shares sentences with these, for which no sentence is quoted: COVID-19 (1 paper).